GBP2 (guanylate binding protein 2)
Diseases named in the same sentence as GBP2 in open-access papers (continued):
Sharing a sentence is not in itself a finding about the gene and the disease.
tuberculosis (3 papers, 2023 to 2025). A chronic, recurrent infection caused by the bacterium Mycobacterium tuberculosis. "Conversely, in pleural tuberculosis, GBP2 expression is elevated in pleural fluid and demonstrates over 80% accuracy in discriminating tuberculosis from other causes of pleural effusion." (PMID 41181145, 2025). "In tuberculosis, GBP2 is consistently downregulated and has been identified as a hub gene with diagnostic potential." (PMID 41181145, 2025). "Other studies demonstrated that GBP2 is aberrantly overexpressed in TB and reduced in pleural tuberculosis patients after anti-TB treatment." (PMID 39337460, 2024). "When the CARD17, GBP2, and C1QB gene expressions in the blood of the non-TB group of patients following anti-tuberculosis therapy were checked, a reduction in the expression of all three genes was found." (PMID 38288122, 2023).
bladder cancer (2 papers, 2021 to 2025). "GSDMB, CLEC2D, APOL2, TNFRSF14, and GBP2 were selected as prognostic genes in bladder cancer patients." (PMID 34708131, 2021).
breast tumors (2 papers, 2020 to 2021). "Results indicated thatthe overall expression of GBP2 was significantly down-regulatedin breast tumors compared with normal adjacent tissues and normal control(p<0.0001)." (PMID 33211060, 2020). "The mean of GBP2 expressionin ductal carcinoma breast tumors was 0.31± 0.28 fold change with the range of0.01 -1 and 0.26 ± 0.26 fold change with the range of 0.01 to 0.93 compared withnormal adjacent tissues and normal control, respectively." (PMID 33211060, 2020). "GBP2 contributes to better clinical outcomes in rapidly proliferating breast tumors and may serve as a marker for an effective T cell response." (PMID 33626234, 2021).
diabetic retinopathy (2 papers, 2022 to 2023). "GBP2 has been identified as a candidate gene in diabetic retinopathy." (PMID 36967805, 2023). "In this study, the key pyroptosis-related genes in diabetic retinopathy, such as CASP3, GBP2, and TLR4, were preliminarily identified by bioinformatics analysis and confirmed by GSE179568 and qRT-PCR in a diabetic model." (PMID 35957838, 2022).
influenza (2 papers, 2020 to 2025). An acute viral infection of the respiratory tract, occurring in isolated cases, in epidemics, or in pandemics; it is caused by serologically different strains of viruses (influenzaviruses) designated A, B, and C, has a 3-day incubation period, and usually lasts for 3 to 10 days. "Interestingly, this cluster expressed high levels of GBP2, shown to exhibit antiviral activity against influenza." (PMID 41143063, 2025).
leukemia (2 papers, 2021 to 2022). A malignant (clonal) hematologic disorder, involving hematopoietic stem cells and characterized by the presence of primitive or atypical myeloid or lymphoid cells in the bone marrow and the blood. "Furthermore, the underlying molecular mechanism of GBP1 and GBP2 as apoptosis inducers, their clinical implications in leukemia, and their efficacy as potential chemotherapeutic agents were investigated." (PMID 34294680, 2021). "Collectively, these results demonstrate that GBP1 and GBP2 induce the mitochondrial apoptotic death of leukemia cells." (PMID 34294680, 2021). "A previous study confirmed that GBP2 induced neuronal apoptosis in traumatic brain injury, and that GBP2 inhibited the PI3K/AKT pathway to induce cell apoptosis in leukemia." (PMID 36091803, 2022). "This reduction in paclitaxel-induced cell death observed in the GBP2 KO cells was effectively reversed by the knock-in of GBP2 in two independent GBP2 KO cell lines, thus confirming that GPB2 is a key mediator of paclitaxel-induced apoptosis in K562 leukemia cells." (PMID 34294680, 2021).
liver dysfunction (2 papers, 2022 to 2025). "The correlation between GBP2 mRNA levels in peripheral leukocytes and liver grafts, along with its consistent upregulation in allogeneic transplantation models, supports its diagnostic utility—particularly in cases accompanied by severe liver dysfunction." (PMID 41181145, 2025). "Moreover, it was previously shown that GBP2 could distinguish between rejection and other kinds of liver dysfunction." (PMID 35281025, 2022). "In patients experiencing acute cellular rejection, GBP2 expression is significantly elevated compared to those with hepatitis C or without severe liver dysfunction following transplantation." (PMID 41181145, 2025).
malaria (2 papers, 2013 to 2021). Malaria is a serious and sometimes fatal disease caused by a parasite that commonly infects a certain type of mosquito which feeds on humans. "We first investigated the effects of nab2, tho4, npl3, gbp2 and sr1 deletion on the asexual development of malaria parasites." (PMID 34604117, 2021). "The reduced male and female gametocyte production by gbp2 deletion mutants in this study implies that during the life cycle of malaria parasites, GBP2 functions during an earlier developmental stage than ALBA4, DOZI and CITH." (PMID 34604117, 2021). "The expression levels of GBP1, GBP2, and TAP1 ranged from 10.6- to 2.8-fold above baseline during early stage of malaria, and the expression level of GBP2 was greater than two-fold change during acute febrile malaria." (PMID 24188121, 2013). "GBP2 localized to both the nucleus and cytoplasm of malaria parasites." (PMID 34604117, 2021). "Our findings imply that NAB2 and GBP2 are involved in nuclear mRNA export in malaria parasites." (PMID 34604117, 2021). "In this study, we focused on GBP2 and NAB2, which play important roles in the sexual and asexual development of malaria parasites, respectively, and examined their cellular localization." (PMID 34604117, 2021). "On the other hand, in the rodent malaria parasite Plasmodium berghei ANKA, GBP2 is primarily involved in sexual development." (PMID 34604117, 2021). "Nuclear poly(A) binding protein 2 (NAB2), THO complex subunit 4 (THO4), nucleolar protein 3 (NPL3), G-strand binding protein 2 (GBP2) and serine/arginine-rich splicing factor 1 (SR1) are involved in nuclear mRNA export in malaria parasites." (PMID 34604117, 2021). "Therefore, to elucidate the quality control and export of mRNA by RNA-binding proteins, we focused on GBP2 and NAB2, which play important roles in the sexual and asexual development of malaria parasites, respectively." (PMID 34604117, 2021). "In this study using the rodent malaria parasite, Plasmodium berghei, we found that NAB2 and SR1, but not THO4, NPL3 or GBP2, played essential roles in the asexual development of malaria parasites." (PMID 34604117, 2021). "We found that NAB2 and SR1, but not THO4, NPL3 or GBP2, played essential roles in the asexual development of malaria parasites." (PMID 34604117, 2021). "IP-MS also revealed that phosphorylated adapter RNA export protein (PHAX) domain-containing protein, an adaptor protein for exportin-1, also interacted with GBP2, implying that mRNA export occurs via the PHAX domain-containing protein pathway in malaria parasites." (PMID 34604117, 2021). "However, the roles of NPL3, GBP2, and SR1 in malaria parasites are not fully understood." (PMID 34604117, 2021). "In malaria parasites, NPL3 and GBP2 were not essential for growth during the asexual stage." (PMID 34604117, 2021).
measles (2 papers, 2021 to 2022). A highly contagious viral infection caused by the measles virus. "GBP2 inhibits a variety of viruses, including human immunodeficiency virus, hepatitis C, swine fever, Zika virus, measles, and influenza A." (PMID 36115937, 2022). "Knockdown of GBP2 and GBP5 led to increased production of HIV-1, and complete depletion of GBP5 also facilitated the replication of influenza A, measles, and Zika viruses." (PMID 33673837, 2021). "Ectopic expression of GBP2 and GBP5 suppressed various viruses' replication, including human immunodeficiency virus-1 (HIV-1), influenza A, murine leukemia, Zika, measles, and Marburg viruses." (PMID 33673837, 2021).
metastatic melanoma (2 papers, 2021). A melanoma that has spread from its primary site to another anatomic site. "However, the expression levels of IFITM1 (P = 0.643) and GBP2 (P = 0.320) were not significantly different between primary and metastatic melanoma tissues." (PMID 33688507, 2021).
osteosarcoma (2 papers, 2023 to 2025). A usually aggressive malignant bone-forming mesenchymal neoplasm, predominantly affecting adolescents and young adults. "In osteosarcoma, GBP2 downregulation enhances migration and invasion, while low GBP2 expression correlates with poor prognosis and metastasis." (PMID 41181145, 2025). "Four gene expression signatures (PLEKHO2, GBP2, MPP1, and VSIG4) linked to osteosarcoma prognosis were identified within the TARGET-osteosarcoma cohort, categorizing patients into two subgroups." (PMID 38169731, 2023). "In vitro experiments provided additional validation by demonstrating that the downregulation of GBP2 promoted the proliferation, migration, and invasion of osteosarcoma cells while inhibiting apoptosis." (PMID 38169731, 2023). "The current study established a prognostic signature associated with TEX-related genes and elucidated the impact of the pivotal gene GBP2 on osteosarcoma cells via in vitro experiments." (PMID 38169731, 2023). "Understanding the precise role of GBP2 in osteosarcoma could potentially pave the way for the development of novel therapeutic strategies targeting this gene to inhibit tumor progression and improve patient outcomes." (PMID 38169731, 2023). "This suggests that GBP2 may possess pro-apoptotic properties in osteosarcoma, and its downregulation may confer a survival advantage to the cancer cells." (PMID 38169731, 2023). "Although PLEKHO2, VSIG4, MPP1, and GBP2 have been implicated in the pathogenesis of several cancers, their roles in osteosarcoma have not been reported to date." (PMID 38169731, 2023). "Thus, we conducted an in-depth investigation into the role of GBP2 in osteosarcoma." (PMID 38169731, 2023). "Therefore, we conducted single-cell RNA-seq analysis of GBP2 expression in osteosarcoma." (PMID 38169731, 2023). "Although the involvement of Guanylate Binding Protein 2 (GBP2) has been well established in the pathogenesis of various tumor types, its specific function in osteosarcoma remains largely unexplored." (PMID 38169731, 2023). "Finally, we focused on investigating the role of GBP2 in osteosarcoma and did not extensively explore the functions of PLEKHO2, VSIG4, and MPP1." (PMID 38169731, 2023).
ovarian carcinoma (2 papers, 2016 to 2025). A malignant neoplasm originating from the surface ovarian epithelium. "CpG‐based nanovaccines bolster ovarian cancer immunotherapy via the Gbp2‐Pin1‐NFkB pathway‐mediated reprogramming of tumor‐associated macrophages (TAMs)." (PMID 39985265, 2025). "The network based approach identified two 7-gene functional interaction modules (31: DCLRE1A, EXO1, KIAA0101, KIN, PCNA, POLD3, POLD2; 35: DKK3, FABP3, IRF1, AIM2, GBP1, GBP2, IRF2) that are associated with prognosis of ovarian cancer patients." (PMID 27806724, 2016).
pancreatic cancer (2 papers, 2021). "The distinct infiltration of immune cells implied that pancreatic cancers with different GBP2 expressions may have different tumor immune microenvironments." (PMID 34026364, 2021).
pulmonary TB (2 papers, 2023 to 2025). "First, studies have confirmed a link between CD4 + TEM cell markers (GBP2 and LAG3) and the risk of pulmonary TB and COVID-19 infection, as the lungs are the primary sites affected by TB, and CD4 + T cells are closely related to TB." (PMID 40295296, 2025). "Based on a reanalytical methodology by bioinformatics that utilizes a previously published transcriptomic public dataset in pulmonary tuberculosis, we succeeded in validating a total of three candidates, CARD17, GBP2, and C1QB genes, in clinical specimens." (PMID 38288122, 2023).
sarcoma (2 papers, 2020 to 2023). A usually aggressive malignant neoplasm of the soft tissue or bone. "After performing validation in both TCGA dataset and GEO dataset GSE17679, we extracted a group of immune-related genes, including NR1H3, VAMP5, GIMAP2, GBP2, HLA-E and CRIP1 that were most significant to predict good outcomes in sarcoma patients." (PMID 33316779, 2020).
Stroke (2 papers, 2024). Sudden impairment of blood flow to a part of the brain due to occlusion or rupture of an artery to the brain. "Stroke increased gene expression of the proinflammatory A1 astrocyte markers Serping1, Psmb8, Srgn, and Gbp2 in both normotensive and hypertensive mice (P < 0.05)." (PMID 38886874, 2024).
subarachnoid hemorrhage (2 papers, 2022 to 2025). A serious neurological disorder characterized by intracranial hemorrhage into the subarachnoid space. "Furthermore, GBP2 expression in subarachnoid hemorrhage‐induced early brain injury indicates its potential impact on neuronal function and survival." (PMID 40242160, 2025).
acute myeloid leukemia (1 paper, 2025). Acute myeloid leukemia (AML) is a group of neoplasms arising from precursor cells committed to the myeloid cell-line differentiation. "Correspondingly, knockdown of GBP2 was shown to significantly increase proliferation and reduce apoptosis in acute myeloid leukemia cells." (PMID 41181145, 2025). "Furthermore, miR-221 promotes acute myeloid leukemia cell proliferation partly through targeting GBP2 and regulating PI3K/AKT pathway activation." (PMID 41181145, 2025).
adenoma (1 paper, 2025). A neoplasm arising from the epithelium. "Specifically, GBP2 and P2RX7 were significantly downregulated in both the “Adenomas and Adenocarcinomas” subtype and the “Cystic, Mucinous and Serous Neoplasms” subtype (p < 0.001), while SLC11A1 and HCLS1 were significantly upregulated in these two subtypes (p < 0.01)." (PMID 41007849, 2025). "The correlation analysis showed consistent results with those of the “Adenomas and Adenocarcinomas” subtype: effector memory CD8+ T cells had the strongest correlation with GBP2 (cor = 0.76, p < 0.001), and the strongest correlation with type 1 T helper cells (cor = 0.87)." (PMID 41007849, 2025).
aneurysm (1 paper, 2026). Bulging or ballooning in an area of an artery secondary to arterial wall weakening. "First, we chose GBP2 as the primary downstream target of ZFP36 for in-depth investigation based on its high expression and substantial variation in AngII-treated VSMCs and aneurysm." (PMID 41551919, 2026).
astrocytoma (1 paper, 2021). "We found that the expressions of GBP1, 2, 3, 4 were significantly increased in astrocytoma vs oligodendroglioma, and GBP2, 3 were highly expressed in oligoastrocytoma vs oligodendroglioma." (PMID 34759950, 2021).
cholangiocarcinoma (1 paper, 2026). A carcinoma that arises from the intrahepatic biliary tree (intrahepatic cholangiocarcinoma) or from the junction, or adjacent to the junction, of the right and left hepatic ducts (hilar cholangiocarcinoma). "Immune profiling and scRNA-seq revealed GBP2's negative correlation with macrophages in fibrosis and positive correlations with T and NK cells in cholangiocarcinoma." (PMID 41898346, 2026).
chronic myeloid leukemia (1 paper, 2025). "Notably, paclitaxel itself can induce GBP2 expression, and GBP2 knockout in chronic myeloid leukemia cells significantly attenuates paclitaxel -induced apoptosis." (PMID 41181145, 2025).
Cirrhosis (1 paper, 2022). A chronic disorder of the liver in which liver tissue becomes scarred and is partially replaced by regenerative nodules and fibrotic tissue resulting in loss of liver function. "We could observe that the A1 subtype-related markers (FKBP5, GBP2, PSMB8, and SRGN) were remarkably elevated in HE samples compared to healthy control samples and cirrhosis samples." (PMID 36424620, 2022).
clear cell renal cell carcinoma (1 paper, 2025). "Similarly, in clear cell renal cell carcinoma, GBP2 overexpression enhances phosphorylation of STAT2 and STAT3, triggering janus kinase(JAK)-STAT signaling and promoting cell migration and invasion." (PMID 41181145, 2025).
Cognitive impairment (1 paper, 2024). Abnormal cognition is characterized by deficits in thinking, reasoning, or remembering. "The study examined the interaction between five hub genes (Cxcl10, Gbp2, Cxcl12, Cxcr3, Ifih1) and four distinct immune cell types (M1 macrophages, NK resting cells, memory CD4 T cells, naive CD8 T cells) in mice brain tissues affected by cognitive impairment." (PMID 39286150, 2024).
diabetic nephropathy (1 paper, 2023). "Nevertheless, the association between GBP2 and macrophage is unknown and GBP2 has not been reported in diabetic nephropathy." (PMID 37622120, 2023).
E. coli infections (1 paper, 2017). "We found that GBP2−/− BMDMs mimicked GBPchr3−/− BMDMs in their unresponsiveness to E. coli infections, as measured by LDH release as a marker of cell death and secretion of IL-1β and IL-18." (PMID 28974614, 2017).